NVL (nuclear VCP like)
Description:
Participates in the assembly of the telomerase holoenzyme and effecting of telomerase activity via its interaction with TERT. Involved in both early and late stages of the pre-rRNA processing pathways. Spatiotemporally regulates 60S ribosomal subunit biogenesis in the nucleolus. Catalyzes the release of specific assembly factors, such as WDR74, from pre-60S ribosomal particles through the ATPase activity.
Synonyms: NVL2
Tractability: Small molecule: a structure with a bound ligand is known. PROTAC: UniProt records ubiquitination sites on it; ubiquitination databases record sites on it; its protein half-life has been measured.
Gene: Protein-coding gene on chromosome 1 (224,227,334 to 224,330,189, reverse strand). Ensembl gene ENSG00000143748.
Subcellular location: Nucleus, nucleoplasm (Isoform 2); Nucleus, nucleolus (Isoform 1); Nucleus, nucleoplasm
Subcellular location (Human Protein Atlas): Nucleoli
Gene Ontology:
Molecular function: ATP binding; preribosome binding; protein binding; RNA binding; ATP hydrolysis activity; protein-containing complex binding
Biological process: positive regulation of protein binding; positive regulation of telomere maintenance; regulation of protein localization to nucleolus; ribosomal large subunit biogenesis; ribosome biogenesis; rRNA processing; telomerase holoenzyme complex assembly
Cellular component: membrane; nuclear exosome (RNase complex); nucleolus; nucleoplasm; nucleus; telomerase holoenzyme complex
Genetic constraint (gnomAD): Loss-of-function variants: 49 observed, 69.69 expected, observed/expected ratio (o/e) 0.7, 90% interval 0.56 to 0.89. The upper end of that interval is the gene's LOEUF score, 0.89, which puts it in group 3 of 6, group 1 being the genes least tolerant of losing a copy. Missense variants: 616 observed, 767.46 expected, observed/expected ratio (o/e) 0.8, 90% interval 0.75 to 0.86. Synonymous variants: 267 observed, 277.99 expected, observed/expected ratio (o/e) 0.96, 90% interval 0.87 to 1.06.
Homologues: Orthologues: chimpanzee NVL (99% identical), macaque NVL (98% identical), pig NVL (92% identical), mouse Nvl (88% identical), rabbit NVL (88% identical), dog NVL (87% identical), guinea pig NVL (87% identical), rat Nvl (85% identical), tropical clawed frog nvl (69% identical), zebrafish nvl (62% identical), Drosophila melanogaster smid (44% identical), Caenorhabditis elegans mac-1 (42% identical). Paralogues in human: VCP (34% identical), AFG2A (33% identical), AFG2B (28% identical), PEX1 (26% identical), PEX6 (25% identical).
Diseases named in the same sentence as NVL in open-access papers:
NVL is named in the same sentence as 13 diseases in open-access papers, as found by Europe PMC text mining. Sharing a sentence is not in itself a finding about the gene and the disease. The quoted sentences say what the papers report.
schizophrenia (3 papers, 2017 to 2024). A major psychotic disorder characterized by abnormalities in the perception or expression of reality. "In the subset of schizophrenia samples where NVL is implicated in DTU, we observed that the NVL1 isoform was preferred, potentially indicating perturbed ribosomal synthesis." (PMID 37503064, 2023). "Among the six candidate genes, four (BDH2, CLDND1, GAS8, and TRIP4) displayed DTU events in all schizophrenia samples, while the other two genes (LARP4 and NVL) showed significant DTU events in specific subgroups." (PMID 38508189, 2024). "Amongst the six candidate genes, four (BDH2, CLDND1, GAS8, TRIP4) displayed DTU events in all schizophrenia samples, while the other two genes (LARP4, NVL) showed significant DTU events in specific subgroups." (PMID 37503064, 2023).
prostate carcinoma (2 papers, 2019 to 2023). A carcinoma that arises from epithelial cells of the prostate gland. "NVL, the gene which encodes for NVL2, has been identified as a prognostic outlier gene for high-risk prostate cancer and shown to confer a risk for mental illness disorders, signifying a need to understand NVL2’s molecular function." (PMID 30705282, 2019). "With siRNA screens, several of these were indicated in survival (DDX6, EIF4A3, PABPN1), growth (e.g., EIF5A, HNRNPH2, LRRC47, and NVL), and migration (e.g., NOL3 and SLTM) of prostate cancer cells." (PMID 37591798, 2023).
calcinosis (1 paper, 2024). Deposition of calcium in the tissues. "The clinical characteristics of these patients revealed that anti-NVL AAb are associated with calcinosis and an increased risk of cancer." (PMID 39906349, 2024).
colorectal cancer (1 paper, 2021). A primary or metastatic malignant neoplasm that affects the colon or rectum. "The minimal value was 4.39, which was attributed to the NVL gene, and it implied that this gene was the most important in the current model in terms of stratifying the recurrence risk of stage II colorectal cancer patients." (PMID 33628243, 2021).
mantle cell lymphoma (1 paper, 2024). Mantle cell lymphoma is a rare form of malignant non-Hodgkin lymphoma affecting B lymphocytes in the lymph nodes in a region called the ``mantle zone''. "One of the anti-NVL-positive patients was diagnosed with mantle cell lymphoma, which is an interesting finding considering that SSc can be paraneoplastic." (PMID 39906349, 2024).
systemic sclerosis (1 paper, 2024). A chronic disorder, possibly autoimmune, marked by excessive production of collagen which results in hardening and thickening of body tissues. "Demographic and clinical characteristics of anti-NVL-positive patients with systemic sclerosis." (PMID 39906349, 2024). "Using line blots coated with recombinant NVL, anti-NVL autoantibodies were exclusively found in four out of 378 patients with systemic sclerosis, but neither in 315 patients with other SARD nor in 150 healthy controls." (PMID 39906349, 2024).
cancer (7 papers, 2019 to 2025). A tumor composed of atypical neoplastic, often pleomorphic cells that invade other tissues. "Finally, we determined the effect of 10 individual factors on OS and observed that higher expression of DKC1, NVL, and GAR1 were significantly associated with nine, three, and three cancer types, respectively." (PMID 36239411, 2023). "In addition, 1 SNP was detected in KMT2C, a BC oncogene, and 9 others were detected in or near 10 genes (SERAC1, DAGLB, MACF1, NVL, FBXW4, FANK1, KCTD4, CAVIN1; ATP6V0A1 and ZBTB20-AS1) previously associated with non-BC cancers." (PMID 35589867, 2022).
infection (1 paper, 2023). The state of being infected such as from the introduction of a foreign agent such as serum, vaccine, antigenic substance or organism. "Consistently, we did not observe any significant co-localisation between translocated 3FLAG-NyxA and LC3 nor with NVL or RPL5 at 48 h post-infection, using cells expressing LC3-GFP to avoid methanol fixation." (PMID 36609656, 2023). "However, infection with L. pneumophila did not result in NVL cytoplasmic accumulation, suggesting this phenomenon is specifically induced during B. abortus infection." (PMID 36609656, 2023). "Although significant NVL staining was still detected in the nucleoli of infected cells, we observed a striking cytoplasmic accumulation of NVL in punctate structures in all B. abortus infected cells at 48 h post-infection that were rarely visible in non-infected cells." (PMID 36609656, 2023).
NVL also shares sentences with these, for which no sentence is quoted: gastric cancer (1 paper); major depressive disorder (1); ovarian carcinoma (1); retinopathy (1); tumor (1).